ZNF222 (zinc finger protein 222)
Description:
May be involved in transcriptional regulation.
Tractability: PROTAC: ubiquitination databases record sites on it.
Gene: Protein-coding gene on chromosome 19 (44,025,337 to 44,033,222, forward strand). Ensembl gene ENSG00000159885.
Subcellular location: Nucleus
Subcellular location (Human Protein Atlas): Nucleoplasm; Nuclear bodies
Pathways (Reactome):
Gene expression (Transcription): Generic Transcription Pathway
Gene Ontology:
Molecular function: DNA-binding transcription factor activity; sequence-specific DNA binding
Biological process: negative regulation of DNA-templated transcription; regulation of DNA-templated transcription
Cellular component: nucleus
Genetic constraint (gnomAD): Loss-of-function variants: 8 observed, 11.94 expected, observed/expected ratio (o/e) 0.67, 90% interval 0.39 to 1.21. The upper end of that interval is the gene's LOEUF score, 1.21, which puts it in group 5 of 6, group 1 being the genes least tolerant of losing a copy. Missense variants: 473 observed, 591.74 expected, observed/expected ratio (o/e) 0.8, 90% interval 0.74 to 0.86. Synonymous variants: 163 observed, 202.93 expected, observed/expected ratio (o/e) 0.8, 90% interval 0.71 to 0.92.
Homologues: Orthologues: chimpanzee ZNF222 (99% identical), macaque ZNF222 (91% identical). Paralogues in human: ZNF223 (77% identical), ZNF230 (76% identical), ZNF155 (76% identical), ZNF233 (43% identical), ZNF214 (40% identical), ZNF285 (40% identical), ZNF527 (36% identical), ZKSCAN7 (36% identical), ZNF34 (36% identical), ZNF287 (35% identical), ZNF852 (35% identical), ZNF416 (34% identical), and 38 more.
Diseases named in the same sentence as ZNF222 in open-access papers:
ZNF222 is named in the same sentence as 1 disease in open-access papers, as found by Europe PMC text mining. Sharing a sentence is not in itself a finding about the gene and the disease. The quoted sentences say what the papers report.
leukemia (1 paper, 2025). A malignant (clonal) hematologic disorder, involving hematopoietic stem cells and characterized by the presence of primitive or atypical myeloid or lymphoid cells in the bone marrow and the blood. "For instance, genes like ANGPT1, PES1, and ZNF222 demonstrated promoter active demethylation by both compounds and are known for promoting cell survival and proliferation of different types of leukemia." (PMID 41516186, 2025).